SPDL1 (spindle apparatus coiled-coil protein 1)
Description:
Required for the localization of dynein and dynactin to the mitotic kinetochore. Dynein is believed to control the initial lateral interaction between the kinetochore and spindle microtubules and to facilitate the subsequent formation of end-on kinetochore-microtubule attachments mediated by the NDC80 complex. Also required for correct spindle orientation. Does not appear to be required for the removal of spindle assembly checkpoint (SAC) proteins from the kinetochore upon bipolar spindle attachment. Acts as an adapter protein linking the dynein motor complex to various cargos and converts dynein from a non-processive to a highly processive motor in the presence of dynactin. Facilitates the interaction between dynein and dynactin and activates dynein processivity (the ability to move along a microtubule for a long distance without falling off the track). Plays a role in cell migration.
Synonyms: hSpindly; CCDC99; FLJ20364
Tractability: PROTAC: UniProt records ubiquitination sites on it; ubiquitination databases record sites on it.
Gene: Protein-coding gene on chromosome 5 (169,583,632 to 169,604,778, forward strand). Ensembl gene ENSG00000040275.
Subcellular location: Cytoplasm, cytoskeleton, microtubule organizing center, centrosome; Chromosome, centromere, kinetochore; Nucleus; Cytoplasm, cytoskeleton, spindle pole
Subcellular location (Human Protein Atlas): Cytosol
Pathways (Reactome):
Cell Cycle: Amplification of signal from unattached kinetochores via a MAD2 inhibitory signal; EML4 and NUDC in mitotic spindle formation; Mitotic Prometaphase; Resolution of Sister Chromatid Cohesion; Separation of Sister Chromatids
Signal Transduction: RHO GTPases Activate Formins
Gene Ontology:
Molecular function: enzyme binding; kinetochore binding; protein binding
Biological process: cell migration; establishment of mitotic spindle orientation; mitotic metaphase chromosome alignment; protein localization to kinetochore; mitotic spindle assembly checkpoint signaling
Cellular component: nucleus; outer kinetochore; spindle pole; cytosol; centrosome
Genetic constraint (gnomAD): Loss-of-function variants: 69 observed, 66.76 expected, observed/expected ratio (o/e) 1.03, 90% interval 0.85 to 1.26. The upper end of that interval is the gene's LOEUF score, 1.26, which puts it in group 5 of 6, group 1 being the genes least tolerant of losing a copy. Missense variants: 609 observed, 632.55 expected, observed/expected ratio (o/e) 0.96, 90% interval 0.9 to 1.03. Synonymous variants: 239 observed, 216.74 expected, observed/expected ratio (o/e) 1.1, 90% interval 0.99 to 1.23.
Homologues: Orthologues: chimpanzee SPDL1 (99% identical), macaque SPDL1 (91% identical), pig SPDL1 (89% identical), guinea pig SPDL1 (84% identical), rabbit SPDL1 (81% identical), dog SPDL1 (81% identical), mouse Spdl1 (74% identical), rat Spdl1 (72% identical), tropical clawed frog spdl1 (54% identical), zebrafish spdl1 (45% identical). Paralogues in human: BICDL1 (14% identical), BICDL2 (13% identical).
Diseases named in the same sentence as SPDL1 in open-access papers:
SPDL1 is named in the same sentence as 165 diseases in open-access papers, as found by Europe PMC text mining. Sharing a sentence is not in itself a finding about the gene and the disease. The quoted sentences say what the papers report.
melanoma (55 papers, 2017 to 2025). A malignant, usually aggressive tumor composed of atypical, neoplastic melanocytes. "Furthermore, the association of PD with change in sPDL1 on treatment is the first biomarker to agree between melanoma and RCC." (PMID 35131863, 2022). "Expression of six Hallmark gene sets was associated with sPDL1 level in the same direction in both RCC and melanoma, indicating a shared underlying tumor biology." (PMID 35131863, 2022).
lung carcinoma (39 papers, 2019 to 2025). "In conclusion, our results revealed that the high SPDL1 expression in lung cancer was linked to poor OS." (PMID 35093072, 2022). "Abnormal expression of SPDL1 is associated with GIN and promotes the development and progression of many cancers including breast, prostate, and lung cancers." (PMID 38623460, 2024). "Inhibition of SPDL1 expression in lung cancer reduced the proliferation of cells and increased their sensitivity to paclitaxel, an MT-based chemotherapeutic agent." (PMID 38623460, 2024). "The comparative analysis of several studies in the Oncomine database also showed that SPDL1 was highly expressed in cervical cancer, colorectal cancer, kidney cancer, head and neck cancer, lung cancer and sarcoma compared with normal tissues (P < .001)." (PMID 35093072, 2022). "Because of an interest in the lung cancer cases, we investigated the correlation between SPDL1 methylation and expression in LUAD and LUSC." (PMID 35093072, 2022). "For lung cancer in TCGA, the relationship between survival prognosis and SPDL1 expression was detected, and we found that high SPDL1 expression was related with poor OS and DFS in LUAD (P = .0015, P = .03, respectively) but not in LUSC (P>.05) based on the GEPIA2 tool." (PMID 35093072, 2022). "However, the correlation between SPDL1 and prognosis in lung cancer was more complicated." (PMID 35093072, 2022). "However, it is noteworthy that SPDL1 expression does not always correlate with immunosensitivity, especially in lung cancer." (PMID 37915003, 2023).
Sepsis (27 papers, 2018 to 2026). Sepsis is defined as life-threatening organ dysfunction caused by a dysregulated host response to infection. "We identified 2 common phenotypes of sepsis survivors based on circulating hs-CRP and sPDL1 levels; approximately two-thirds had persistent elevation of both inflammation and immunosuppression biomarkers, and a third had normal biomarkers." (PMID 31390038, 2019). "First, patients may have had high hs-CRP and sPDL1 levels before sepsis occurred rather than a consequence of sepsis." (PMID 31390038, 2019).
gastric cancer (25 papers, 2017 to 2025). A primary or metastatic malignant neoplasm involving the stomach. "This suggested that the SPDL1 gene worked differently in gastric cancer." (PMID 35093072, 2022). "In contrast, lowly expressed SPDL1 was related to poor OS (P < .001), first progression (FP) (P < .05) and PPS (P < .001) in gastric cancer." (PMID 35093072, 2022).
breast carcinoma (18 papers, 2020 to 2026). "Based on the Kaplan-Meier plotter, a high SPDL1 expression level was associated with poor OS, DMFS, PPS, RFS in breast cancer." (PMID 35093072, 2022). "Protein expression of SPDL1 was higher in the primary tumor tissues than normal tissues of breast cancer, LUAD and UCEC (P < .001) in the CPTAC dataset." (PMID 35093072, 2022). "In the TCGA dataset, C11orf1, OLA1, RPL31, SPDL1 and IL33 were identified to be associated with prognosis of breast cancer." (PMID 35761863, 2022). "The comparison of the SPDL1 phosphorylation levels between normal tissues and primary tumor tissues was analyzed in breast cancer and ovarian cancer with the CPTAC dataset." (PMID 35093072, 2022). "SPDL1 was upregulated in bladder cancer, breast cancer, cholangiocarcinoma, ESCA, squamous cell cancer in the head and neck region, kidney renal clear cell carcinoma, and other tissues, but was downregulated in kidney chromophobe tissues." (PMID 35664322, 2022). "Interestingly, when we analyzed the patients with negative ER and positive PR of breast cancer, SPDL1 low expression is significantly correlated with poor OS." (PMID 35093072, 2022).
COVID-19 (17 papers, 2021 to 2026). A disease caused by infection with severe acute respiratory syndrome coronavirus 2. "In conclusion, this study demonstrated that sCD27, sHVEM, sTIM-3, sPD-1, and sPDL-1 levels were significantly higher in patients with severe COVID-19 than those with moderate disease." (PMID 38809008, 2024). "By combining sPDL-1 levels with the number of peripheral lymphocytes and sPDL-1 levels with CRP levels, we highlighted the dynamic role of sPDL-1 in modulating the immune and inflammatory response during COVID-19." (PMID 37959277, 2023).
colorectal cancer (14 papers, 2019 to 2026). A primary or metastatic malignant neoplasm that affects the colon or rectum. "The Reactome Pathway and KEGG BRITE databases were then applied to identify the SPDL1-related pathways and functional hierarchies, respectively, possibly implicated in colorectal cancer." (PMID 35163739, 2022). "A previous study reported that SPDL1 was a tumor suppressor gene for colorectal cancer (CRC), which acted in the downstream of MRTFB to regulate CRC growth." (PMID 35093072, 2022). "SPDL1 was defined as a candidate tumor suppressor in colorectal cancer (CRC) to play an essential role in the downstream of Myocardin-related transcription factor B (MRTFB) that could regulate CRC growth and survival." (PMID 35093072, 2022). "We further adjusted our estimates for confounder bias, and found that SPDL1-low mRNA expression was a negative prognostic factor in colorectal cancer independently of age at diagnosis, gender, and TNM parameters stage." (PMID 35163739, 2022). "Hence, wet-laboratory studies on SPDL1 and correlated pathways in CRC are warranted, as they may provide some novel insights into the mechanism of genomic instability in colorectal cancer." (PMID 35163739, 2022).
lymph node metastasis (14 papers, 2020 to 2025). "The relationship between SPDL1 expression level and clinicopathological data (age, gender, grade, T stage, lymph node metastasis, nerve invasion, and vascular invasion) of ESCA patients was investigated." (PMID 35664322, 2022). "In 53 ESCA patients, SPDL1 expression was significantly correlated with SUVmax, SUVmean, and TLG of PET/CT, and was not related to the age, gender, grade, T stage, lymph node metastasis, nerve invasion, and vascular invasion." (PMID 35664322, 2022).
ovarian carcinoma (10 papers, 2019 to 2025). A malignant neoplasm originating from the surface ovarian epithelium. "We observed that high expression of SPDL1 was associated with poor OS, RFS, PPS in ovarian cancer, especially in subgroups, such as “grade 4”, “stage I, III, IV”." (PMID 35093072, 2022). "More experiments are needed to confirm the roles of SPDL1 in prognosis of ovarian cancer." (PMID 35093072, 2022). "The SPDL1 phosphorylation levels in S555 was enhanced in ovarian cancer." (PMID 35093072, 2022).
esophageal cancer (9 papers, 2022 to 2024). A primary or metastatic malignant neoplasm involving the esophagus. "Inhibiting the expression of spindle appendix cooled coil protein 1 (SPDL1) can slow down disease progression and is related to poor prognosis in patients with esophageal cancer." (PMID 39196978, 2024).
clear cell renal cell carcinoma (7 papers, 2019 to 2024). "Moreover, in an exploratory study, both sPDL1 and sCTLA4 were correlated with poor outcome in patients with metastatic renal clear cell carcinoma treated with tyrosine kinase inhibitors (TKI)." (PMID 34357118, 2021).
lung adenocarcinoma (7 papers, 2017 to 2025). A carcinoma that arises from the lung and is characterized by the presence of malignant glandular epithelial cells. "The expression of SPDL1 was also further verified by immunohistochemistry (IHC) in lung adenocarcinoma (LUAD) tissues." (PMID 35093072, 2022). "However, whether ILC2 and M2 macrophages jointly maintain T cell exhaust and their relationship with sPD1 and sPDL1 in peripheral blood of patients with lung adenocarcinoma, it has not been further explored." (PMID 36479137, 2022).
biliary tract cancer (5 papers, 2016 to 2024). "In this study, we measured the serum level of sPDL1 and evaluated its prognostic implication in biliary tract cancer (BTC)." (PMID 27780932, 2016). "In parallel, as a prognostic factor, the more strength of sPDL1 compared with NLR, which is a very pragmatic, easily applicable clinical factor for the practice on advanced biliary tract cancer patients, should be studied." (PMID 27780932, 2016).
idiopathic pulmonary fibrosis (5 papers, 2021 to 2025). Idiopathic pulmonary fibrosis (IPF) is a nonneoplastic pulmonary disease that is characterized by the formation of scar tissue within the lungs in the absence of any known cause. "Common and rare genetic variants at the KIF15 (kinesin family member 15) gene, and a rare variant in SPDL1 (spindle apparatus coiled-coil protein 1) have also been associated with pulmonary fibrosis." (PMID 37965228, 2023).
cutaneous melanoma (4 papers, 2022 to 2024). A primary melanoma arising from atypical melanocytes in the skin. "We assessed the expression of SPDL1 between the normal tissues and tumor tissues of DLBC, Acute Myeloid Leukemia (LAML), LGG, Sarcoma (SARC), Skin Cutaneous Melanoma (SKCM), Thymoma (THYM) (P < .01)." (PMID 35093072, 2022).
pancreatic ductal adenocarcinoma (4 papers, 2022 to 2025). An infiltrating adenocarcinoma that arises from the epithelial cells of the pancreas. "This hypothesis was put forward in the previous reports, including our recent one linking high levels of SPDL1 with genomic instability in pancreatic ductal adenocarcinoma and oral squamous cell carcinoma." (PMID 35163739, 2022). "The results of the present study are in agreement with our recent data on pancreatic ductal adenocarcinoma; however, opposite findings have been made in oral squamous cell carcinoma, where SPDL1 overexpression was reported to be related to CIN and worse outcome." (PMID 35163739, 2022). "In addition, SPDL1 overexpression correlated with the poor prognosis of the patients with different malignancies, such as colorectal cancer (CRC), pancreatic ductal adenocarcinoma, oral squamous cell carcinoma (OSCC), lung cancer, and esophageal cancer (ESCA)." (PMID 39148981, 2024).
prostate carcinoma (4 papers, 2024 to 2025). A carcinoma that arises from epithelial cells of the prostate gland. "In addition to TERT, we found rare non-synonymous variants in three genes associated with decreased prostate cancer risk (ANO7, SPDL1 and AR), and three genes associated with increased risk (HOXB13, CHEK2 and BIK)." (PMID 39971927, 2025).
liver cancer (3 papers, 2022 to 2024). An epithelial or non-epithelial malignant neoplasm that arises from the liver. "The results revealed that high SPDL1 expression was correlated with the poor OS, distant metastasis-free survival (DMFS), progress-free survival (PFS) and relapse-free survival (RFS) in liver cancer (P < .001)." (PMID 35093072, 2022).
pancreatic adenocarcinoma (3 papers, 2021 to 2024). "Collectively, the present study is the first to investigate cyclin F and SPDL1 proteins in pancreatic adenocarcinoma, and one of the few that assessed RRM2 in this group of cancer patients." (PMID 33670609, 2021).
liver cirrhosis (2 papers, 2022 to 2023). "The hub gene set variation analysis (HGSVA) score of the gene set, which include the SPDL1, may reflect the pathological progression from liver cirrhosis to HCC, and SPDL1 expression was an independent prognostic factor for both OS and RFS." (PMID 35093072, 2022).
esophageal squamous cell carcinoma (1 paper, 2024). Esophageal squamous cell carcinoma (ESCC) is a type of esophageal carcinoma (EC) that can affect any part of the esophagus, but is usually located in the upper or middle third. "However, the specific roles and molecular mechanisms of SPDL1 in esophageal squamous cell carcinoma (ESCC) have not been explored yet." (PMID 39196978, 2024).
osteosarcoma (1 paper, 2022). A usually aggressive malignant bone-forming mesenchymal neoplasm, predominantly affecting adolescents and young adults. "This is in contrast to human osteosarcoma U2OS cells and primary fibroblasts lacking SPDL1, which migrated slower in 2D cell culture than control cells." (PMID 35163739, 2022).
type 1 diabetes (1 paper, 2024). "We measured the concentrations of 14 sICM (sBTLA, sCD27, sCD28, sCD80, sCD137/4–1BB, sCTLA-4, sGITR, sHVEM, sIDO, sLAG-3, sPD-1, sPDL-1, sPDL-2 and sTIM-3) in the sera of the 57 AAb+ children compared with 79 children with recent-onset type 1 diabetes and 44 healthy children." (PMID 38214712, 2024).